IL13 (interleukin 13)
Diseases named in the same sentence as IL13 in open-access papers (continued):
Sharing a sentence is not in itself a finding about the gene and the disease.
amebiasis (1 paper, 2022). A parasitic infectious disorder caused by amoebas. "At baseline and after amebic infection, there was a significantly higher IL13+ILC2s in C57BL/J mice, which are naturally resistant to amebiasis, than CBA/J mice." (PMID 34400793, 2022).
amoebic colitis (1 paper, 2019). "In addition to systemic and local induction of IL-13 and IL-5, a possible role of IL-25 can be hypothesized, as it has recently been shown in protection from amoebic colitis, acting via eosinophils and suppression of TNF-α through a new pathway of innate mucosal immune response." (PMID 31212833, 2019).
angiosarcoma (1 paper, 2025). A malignant tumor arising from the endothelial cells of the blood vessels. "While our findings demonstrate that IL-13 promotes angiosarcoma proliferation, the precise underlying mechanisms remain elusive." (PMID 40855097, 2025). "Knockdown experiments and neutralizing antibody studies corroborated the critical role of the IL-13-IL-13Rα2 axis in driving angiosarcoma cell proliferation." (PMID 40855097, 2025). "These histological observations indicate that IL-13 exists in the environment surrounding angiosarcoma cells." (PMID 40855097, 2025). "We next investigated the effect of IL-13 on angiosarcoma proliferation by experiments with IL-13 supplementation." (PMID 40855097, 2025). "Immunolabelling for IL-13 showed strong signals in a subset of tumor cells from angiosarcoma patients, particularly in atypical tumor cells forming luminal structures." (PMID 40855097, 2025). "Given the multitude of potential pathways involved, further investigation is necessary to identify additional mechanisms in IL-13-mediated angiosarcoma progression." (PMID 40855097, 2025). "The effect was inhibited by siRNA-mediated knockdown of IL13RA2 or neutralizing antibodies against IL-13, suggesting the impact of IL-13/IL-13Rα2 axis in the angiosarcoma proliferation." (PMID 40855097, 2025). "Our findings revealed that IL-13 is present in the angiosarcoma microenvironment, with strong expression observed in atypical tumor cells." (PMID 40855097, 2025). "On a related note, we also considered it necessary to confirm the abundance of the IL-13Rα2 receptor ligand, IL-13 in angiosarcoma tissue." (PMID 40855097, 2025). "Functional studies showed that IL-13 promotes angiosarcoma cell proliferation, an effect mediated primarily through IL-13Rα2." (PMID 40855097, 2025). "Given the difficulty in isolating primary angiosarcoma cells from patients, we first examined the mRNA expression of IL-13 receptors using recently established and reported angiosarcoma cell lines ISO-HAS-B and MO-LAS-B to investigate the effect of IL-13 on angiosarcoma." (PMID 40855097, 2025). "The role of interleukin-13 (IL-13) and its receptors in angiosarcoma pathogenesis has been largely unknown." (PMID 40855097, 2025). "Based on these expression analyses, we proceeded to investigate the effects of IL-13 and its receptors in angiosarcoma to further characterize their functional significance using MO-LAS-B cells which showed the highest expression of IL-13Rα2 in our QPCR analysis." (PMID 40855097, 2025). "This study investigated the role of IL-13 and its receptors in angiosarcoma pathogenesis." (PMID 40855097, 2025). "Moreover, histological analysis showed the presence of IL-13 in the angiosarcoma microenvironment." (PMID 40855097, 2025). "Functional studies using angiosarcoma cell lines, MO-LAS-B cells, revealed the promoting effect of IL-13 on cell proliferation." (PMID 40855097, 2025).
anthrax (1 paper, 2015). "Thus, cutaneous anthrax induces a broad T cell memory response characterized not only by the presence of Th1 cytokines IFNγ and TNFα, but also Th2 (IL-5 and IL-13), Th17 (IL-17/IL-22), Th22 (IL-22) and Th9 (IL-9) cytokines and a potentially regulatory IL-10 response." (PMID 26075052, 2015).
aseptic meningitis (1 paper, 2023). Inflammation of the membranes surrounding the brain and spinal cord without a bacterial pathogen. "Despite being significantly raised in TBM compared with bacterial, viral and aseptic meningitis, there is no literature investigating the role of IL-13 in TBM." (PMID 38264653, 2023).
aspergillosis (1 paper, 2016). Aspergillosis is an infection, growth, or allergic response caused by the Aspergillus fungus. "The A allele (glutamine) of rs20541 and the T allele of rs1800925 may increase susceptibility to ABPA by increasing IL13 expression and increasing the allergic Th2 response, including IgE production, which is detrimental in aspergillosis." (PMID 27708669, 2016).
atrial fibrillation (1 paper, 2018). A disorder characterized by an electrocardiographic finding of a supraventricular arrhythmia characterized by the replacement of consistent P waves by rapid oscillations or fibrillatory waves that vary in size, shape and timing and are accompanied by an irregular ventricular response. "Conversely, lower levels of CCL3, IL-12, IL-5, IL-10, IL-13 were observed in the ZIKV-infected patient with atrial fibrillation as compared to the healthy controls." (PMID 29370812, 2018).
autoimmune uveitis (1 paper, 2023). An autoimmune form of uveitis (disease). "It is worth noting that IL-2, IL-6, IL-13, IL-18, IFN-γ, and TNF-α were significantly higher in the aqueous humor of children with JIA-associated autoimmune uveitis." (PMID 36969183, 2023).
bacterial pneumonia (1 paper, 2020). Acute infection of the lung parenchyma caused by bacteria (e.g., Streptococcus pneumoniae, Haemophilus influenzae, Chlamydia pneumoniae, Mycoplasma pneumoniae, and Legionella pneumophila). "Cytokines IL-4 and IL-13 in lung are shown to play important roles in driving M2 polarization of alveolar macrophages (AMs), which could result in the susceptibility of mice to bacterial pneumonia." (PMID 32200357, 2020).
bile duct disorder (1 paper, 2020). A disease involving the bile duct. "This is the first study showing that IL-13-depletion could be a therapeutic approach for the treatment of patients with bile duct disorders." (PMID 32846954, 2020).
bladder tumor (1 paper, 2023). "Upon in vitro stimulation, ILC2s from both bladder tumor-free and tumor-bearing mice secreted IL-13, with a significant increase in secretion levels observed in the presence of the tumor." (PMID 38283350, 2023). "Targeting ILC2s by blocking IL-4/IL-13 signaling pathways, IL-5, or IL-33 receptor, or using IL-33-deficient or ILC2-deficient mice, did not affect mice survival following bladder tumor implantation." (PMID 38283350, 2023). "However, the absence of ILC2s in these mice did not affect the mice survival following bladder tumor challenge, in line with the results obtained when blocking IL-4/IL-13 or IL-5 signaling pathways, or IL-33/ST2 axis." (PMID 38283350, 2023).
blepharitis (1 paper, 2022). Inflammation of the eyelids near the eyelashes. "IL-4 and IL-13 are among main cytokines involved in Th2 driven immune response; blocking IL-4 and IL-13 with dupilumab may cause increased risk of eye infections (conjuntivitis, blepharitis, cheratitis) and oral herpes." (PMID 36619513, 2022).
blepharoconjunctivitis (1 paper, 2020). Inflammation of both the eyelids and the conjunctiva. "Although the underlying mechanism of blepharoconjunctivitis in AD patients is still not completely elucidated, some authors have suggested that the blockade of IL-4 and IL-13 may increase the activity of specific ligands, such as OX40 ligand, involved in atopic keratoconjunctivitis." (PMID 32183179, 2020).
carcinoid (1 paper, 2013). "Recently we have identified a role of IL-13 in murine EC cell biology and BON cell hyperplasia, BON cells are human carcinoid cells that secrete 5-HT thus used as a model of EC cells." (PMID 24015275, 2013).
cellulitis (1 paper, 2022). Inflammation of the dermis and subcutaneous tissues caused by a bacterial infection. "However, long-term treatment with immunosuppressive agents such as fingolimod and IL-4/IL-13-neutralizing antibodies may be a risk factor for infection (e.g., cellulitis)." (PMID 35886961, 2022).
cerebral artery occlusion (1 paper, 2022). "Thus, we examined the effect of IL-13 on long-term recovery and microglia/macrophage polarization in mice with transient middle cerebral artery occlusion model (tMCAO)." (PMID 35578342, 2022).
cervical adenocarcinoma (1 paper, 2021). An adenocarcinoma arising from the cervical epithelium. "IL4 and IL13 can upregulate CD44 expression in human cervical adenocarcinoma cell lines and colonic epithelial cell lines." (PMID 35187044, 2021).
cholera (1 paper, 2021). "A major effect of IL-13 is in inducing goblet cell differentiation, resulting in the production of excess mucus, a well characterized result of cholera disease." (PMID 34888255, 2021). "Additionally, the cytokine IL-13 was shown to be significantly elevated and paralleled the mucin output in zebrafish excretions, strengthening our knowledge of IL-13 induced mucin production in cholera." (PMID 34888255, 2021). "In addition, this study provides a direct link between excess mucus production during cholera and IL-13 cytokine responses." (PMID 34888255, 2021). "While IL-13 levels have been assessed, these studies are generally done in investigations of CD4+ cell responses to cholera." (PMID 34888255, 2021). "Though mucin production is well known to occur during V. cholerae infection, and IL-13 production is established as an inducer of goblet cell differentiation and mucus secretion, evidence linking these together during cholera is currently lacking." (PMID 34888255, 2021).
chronic cholecystitis (1 paper, 2025). "We suggest that in the gallbladder wall of patients with chronic cholecystitis, IL-13 might participate in feedback loops to regulate the intensity of chronic inflammation." (PMID 40003307, 2025).
chronic heart failure (1 paper, 2018). "In this sense, a previous work showed that IL-13 serum levels significantly increase as the severity of T2D-related chronic heart failure also increases." (PMID 29675435, 2018).
chronic hepatitis C (1 paper, 2018). "In another study, chronic hepatitis C patients presented elevated serum levels of IL-10, IFN-γ, IL-6, and IL-4, while IL-1, IL-2, IL17, IL-22, IL-13 TNF, IL-12p70, and IL-15 levels were lower in patients compared to healthy controls." (PMID 29977152, 2018).
CINCA syndrome (1 paper, 2021). Chronic Infantile Neurological, Cutaneous, and Articular (CINCA) syndrome is characterized by skin rash, joint involvement, chronic meningitis with granulocytes and, in some cases, sensorineural hearing loss and ocular signs. "CINCA syndrome is a rare AIED with autosomal dominant inheritance, and is linked with NLRP3 variants which cause hyper-activation of inflammasomes and excessive release of interleukin-13." (PMID 34580346, 2021).
clostridium difficile infection (1 paper, 2025). Symptomatic infection due to the spore-forming bacterium clostridium difficile. "However, recent studies have shown that secretion of IL-5 and IL-13 from ILC2s protects mice against toxin-mediated epithelial damage during Clostridium difficile infection (CDI)." (PMID 40591723, 2025).
CO poisoning (1 paper, 2025). "In summary, this MR study provides genetic evidence supporting a potential causal role of IL-10, IL-1β, and IL-13 in the pathogenesis of CO poisoning." (PMID 40988268, 2025). "In the context of CO poisoning, where a prompt and effective inflammatory response might be crucial for limiting initial damage, overexpression of IL-10 and IL-13 may paradoxically inhibit protective responses." (PMID 40988268, 2025).
coccidioidomycosis (1 paper, 2023). A fungal infection caused by Coccidioides immitis. "In patients with pulmonary coccidioidomycosis, several cytokines were increased in high concentrations, including granulocyte-macrophage colony-stimulating factor (GM-CSF), interleukin-1β (IL-1β), interferon gamma (IFN-γ), IL-2, IL-13, and tumor necrosis factor alpha (TNF-α)." (PMID 37233224, 2023).
colon adenocarcinoma (1 paper, 2020). "Consistently, Biton's study found that IL-13 stimulation induces miR-375 expression in HT-29 human colon adenocarcinoma cells." (PMID 32802247, 2020).
contact dermatitis (1 paper, 2021). An inflammatory skin condition caused by direct contact between the skin and either an irritating substance or an allergen. "DNCB is a substance that causes contact dermatitis through increasing serum immunoglobulin E (IgE) or Th2 cytokine levels (IL-4, IL-13, etc.)." (PMID 34944580, 2021).
cryptosporidiosis (1 paper, 2016). Intestinal infection with organisms of the genus Cryptosporidium. "Consequently, like in malnourished children with active cryptosporidiosis, either peak primary C. parvum challenge during PM in mice or stimulation of their naïve lymphocytes with C. parvum antigens elicits a basal IL13 response rather than IFNγ." (PMID 27467505, 2016). "In contrast, stool cytokines in malnourished children with active cryptosporidiosis demonstrate increased TNF-α, IL-8, and IL-13, and serum IgE, but not IgG is elevated." (PMID 27467505, 2016).
Darier disease (1 paper, 2025). Darier disease (DD) is a keratinization disorder characterized by the development of keratotic papules in seborrheic areas and specific nail anomalies. "Dupilumab, a monoclonal antibody targeting IL-4 and IL-13, has shown excellent efficacy in alleviating pruritus in other dermatologic conditions and may also help manage itch in patients with Darier disease, as evidenced by a recent case report." (PMID 40142630, 2025).
deafness (1 paper, 2019). An inherited or acquired condition characterized by the complete loss of the ability to hear from one or both ears. "In contrast, IL-13 and IL-9 concentrations were higher in patients with complete deafness (surditas, SDT) compared to patients with residual hearing (*p < 0.05) although statistical significance was missed for IL-9 (p = 0.058)." (PMID 31293504, 2019).
delirium (1 paper, 2022). A disorder characterized by confusion; inattentiveness; disorientation; illusions; hallucinations; agitation; and in some instances autonomic nervous system overactivity. "In this case, finding seems to suggest that, during differentiation, the detrimental effect on neurogenesis and apoptosis caused by the high IL6 concentrations in serum from delirium patients is mediated by production of IL13." (PMID 36195636, 2022). "The causal role of IL6 and IL6-induced IL12 and IL13 in mediating the effect of serum from delirium patients on the neurogenic outcomes is confirmed by the use of an antibody against these cytokines in our experiments." (PMID 36195636, 2022). "Indeed, treatment with an antibody against IL12 or IL13 prevented the effect of serum from delirium patients on cell proliferation, cell differentiation and apoptosis." (PMID 36195636, 2022). "Of note, treatment with serum from delirium patients induced our cells to produce two well-known inflammatory cytokines, IL12 and IL13, in the supernatant; these cytokines were in very low quantities in serum, indicating a direct production by cells." (PMID 36195636, 2022). "Moreover, increased concentration of IL6 in serum samples from delirium patients stimulated the hippocampal cells to produce IL12 and IL13, and treatment with an antibody against IL12 or IL13 also prevented the decreased cell proliferation and neurogenesis, and the increased apoptosis." (PMID 36195636, 2022).
Diffuse Systemic Sclerosis (1 paper, 2023). "Romilkimab, an anti-IL-4 and anti-IL-13 antibody, has shown promising results in animal models and is currently undergoing Phase II trials (Effectiveness and Safety of SAR156597 in Treating Diffuse Systemic Sclerosis, NCT02921971)." (PMID 37035331, 2023).
dilatation (1 paper, 2022). "Collectively, these results are consistent in showing that the combined cardiac overexpression of IL9, IL3, IL4, IL13, and IL15 during the chronic phase of CVB3-induced VM can significantly improve the outcome of cardiac disease, reducing cardiac dilatation and dysfunction." (PMID 35508525, 2022).
Disseminated intravascular coagulation (1 paper, 2023). Disseminated intravascular coagulation is characterized by the widespread activation of coagulation, which results in the intravascular formation of fibrin and ultimately thrombotic occlusion of small and midsize vessels. "Biopsies obtained at the end of the study period did not demonstrate evidence of hyperacute rejection, disseminated intravascular coagulation (DIC), hyperinflammation, excessive cytokine release (IL-2, IL-6, IL-10, IL-13), or complement dysregulation." (PMID 38020483, 2023).
Dry skin (1 paper, 2024). Skin characterized by the lack of natural or normal moisture. "The inflammation associated with this dry skin pathogenesis arises from IL-33 production in keratinocytes, and it is accompanied by leukocyte infiltration and elevated IL-13 production from dermal ILC2s." (PMID 38319737, 2024).
Duchenne muscular dystrophy (1 paper, 2025). Duchenne muscular dystrophy (DMD) is a neuromuscular disease characterized by rapidly progressive muscle weakness and wasting due to degeneration of skeletal, smooth and cardiac muscle. "Contrary to prior data, this study shows that neither eosinophils nor STAT6-mediated IL-4/IL-13 signaling contribute significantly to muscle repair after acute injury or in Duchenne muscular dystrophy (DMD) models." (PMID 39900735, 2025).
Dupuytren’s disease (1 paper, 2020). "IL-13 is implicated in aberrant responses involved in fibrotic disease, and we aimed to understand its role in the inflammatory processes of a common fibrotic disorder, Dupuytren’s disease." (PMID 32695877, 2020). "A proportion (mean, 21.01 ± 6.53%) of CD117+ mast cells did express IL-13, suggesting that mast cells are the primary source of IL-13 in Dupuytren’s disease." (PMID 32695877, 2020). "Here, we report immune cell–driven IL-13 production and signaling in Dupuytren’s disease, which enhances the fibroproliferative features of the tissue response primarily through increased IL-13Rα1 signaling." (PMID 32695877, 2020). "Given that targeting inflammatory pathways has proven encouraging in other fibrotic disorders, we investigated the role for IL-13 signaling as a potential therapeutic target in Dupuytren’s disease." (PMID 32695877, 2020). "Together, these data suggest IL-13 is predominantly released from mast cells in Dupuytren’s disease following cytokine exposure." (PMID 32695877, 2020). "In summary, the current study establishes inflammation-driven epigenetic changes in fibroblasts and IL-13 production in the pathogenesis of Dupuytren’s disease." (PMID 32695877, 2020). "As these pathways are vital for increased IL-13 production and signaling, we explored the use of this inhibitor as a potential therapeutic intervention in Dupuytren’s disease." (PMID 32695877, 2020). "As one of the main hallmarks of Dupuytren’s disease is dysregulated matrix deposition, particularly collagen, and as IL-13 is known to directly affect matrix protein production, we sought to determine the effect of IL-13 on matrix gene expression in both control and diseased cells." (PMID 32695877, 2020). "S3A) has a key role in manifesting the enhanced effects of IL-13 via up-regulation of IL-13Rα1 in Dupuytren’s disease, we investigated whether differential STAT1 binding at the IL-13Rα1 gene locus may cause this to enhance its activity by performing ChIP enrichment analysis." (PMID 32695877, 2020). "While we demonstrate effective targeting of IL-13 production and signaling, we acknowledge a critical role of TGF-β in driving Dupuytren’s disease." (PMID 32695877, 2020).
E. coli infection (1 paper, 2015). "The anti-inflammatory cytokine genes for both IL10 and IL13 were expressed at very low levels and there was no significant increase in their expression 3 h after inoculation, while expression of genes for receptors for both these cytokines increased in response to E. coli infection." (PMID 26572250, 2015).